PTGS1 (prostaglandin-endoperoxide synthase 1)
Diseases named in the same sentence as PTGS1 in open-access papers (continued):
Sharing a sentence is not in itself a finding about the gene and the disease.
tumor (continued). "Importantly, Ptgs1/Ptgs2−/− tumors were able to grow in Rag1−/−, Tap1−/−, and Batf3−/− hosts, indicating that prostanoid deficiency did not impair tumor formation in a cell-intrinsic fashion but rather acted to prevent CD8α+/CD103+ DC-dependent rejection mediated by CD8+ T lymphocytes." (PMID 26343581, 2015). "The importance of this NK cell–cDC1 axis has been well demonstrated in tumor models lacking the Ptgs1 and Ptgs2 genes, which are required to produce the immunosuppressive prostaglandin PGE2." (PMID 40410571, 2025). "The RT-qPCR analysis showed that PLCE1, ST8SIA1, ST3GAL5, and GBA2 were aberrantly regulated between the tumor and nontumor cell lines, while the results of PTGS1 and AMT showed no significance." (PMID 38454278, 2024). "Similarly, after their culture with ECs, IL30-overexpressing PCs showed a dramatic upregulation of a wide range of oncogenes, which included CCND2, EGR3, IGFBP5, KLK3, PDLIM4, PTGS1 and SHBG and a few tumor suppressors, such as GPX3, FOXO1, MAX and NKX3-1." (PMID 38087324, 2023). "In tumors derived from both cell lines, we found eicosanoid synthases (Ptgs1, Ptgs2, Hpgds, Alox5) to be more highly expressed in immune cells than in tumor cells although expression is not exclusive (Figure A3A and B; Table A2)." (PMID 36277993, 2022). "High levels of CCL5 protein in lysates from Ptgs1/Ptgs2−/− BRAFV600E tumors but not control BRAFV600E tumor lysates were confirmed by cytometric bead array (CBA) analysis." (PMID 29429633, 2018). "The opposite trend was observed with PTGER4, PTGDS, PTGER3, PTGIS, PTGFR, and PTGS1 genes, which showed overexpression in the adjacent non-tumor tissue, followed by downregulation in the tumor." (PMID 26207152, 2015). "Because PTGS1 can be inhibited by widely used non-steroidal anti-inflammatory drugs, immunohistochemistry was performed for evaluation if the tumour cells showed a corresponding protein expression." (PMID 24398114, 2014). "We found elevated expression of PTGS2 (P<0.001) but not PTGS1 in PTGER4 xenograft tumours compared with WT tumours." (PMID 21589857, 2011). "In addition, antibody-mediated depletion of NK cells in WT or Rag1−/− mice resulted in a decrease in cDC1 within Ptgs1/Ptgs2−/− BRAFV600E tumors irrespective of total tumor mass." (PMID 29429633, 2018). "Interestingly, we found that expression of PTGS2 but not PTGS1 was elevated in PTGER4 tumour xenografts compared with WT xenografts." (PMID 21589857, 2011). "Notably, Ptgs1/2 deletion fully re-sensitized RTT tumours to ACT and grew unperturbed without ACT." (PMID 39604727, 2025). "However, whereas the numbers of differentiated TIM-3+ TILs were low in control BRAFV600E tumours in WT mice and Ptger2−/−Ptger4fl/fl mice, they were highly abundant in Cd4crePtger2−/−Ptger4fl/fl mice and indistinguishable from those found in Ptgs1/Ptgs2−/− BRAFV600E tumours in WT mice." (PMID 38658748, 2024). "As depicted by the results, there was no marked difference in PTGS1 and AMT expression between tumor and normal cell lines." (PMID 38454278, 2024). "Within the tumor population, we identified expression of phospholipase enzymes PLA2G2A and PLA2G4A and PTGS2 (COX2), but not PTGS1 (COX1)." (PMID 36277993, 2022). "Similar to Ptgs1/Ptgs2−/− BRAFV600E tumors, B16-OVA tumors (that do not produce PGE2) expressing CCL5 and XCL1 showed increased accumulation of cDC1 within the TME and decreased tumor growth." (PMID 29429633, 2018).
cancer (40 papers, 2008 to 2026). A tumor composed of atypical neoplastic, often pleomorphic cells that invade other tissues. "PTGS1 has been implicated in numerous pathophysiological processes including arthritic disease, cancer, pain, and inflammation, but its role in osteogenic differentiation and inflammatory regulation in MSCs remains fairly vague." (PMID 30760327, 2019). "To understand the role of cancer-cell-derived PGE2 in immune evasion, we ablated PGE2 production through cyclooxygenase-1 (COX1; encoded by Ptgs1) and COX2 (encoded by Ptgs2) KO in RTT cells and engrafted them into Rag2–/– mice." (PMID 39604727, 2025). "PTGS1 is also perceived as acting critical roles on pathophysiological progress of inflammation, arthritic disease, and cancer." (PMID 30760327, 2019). "For example, overexpression of COX-1 leads to tumorigenic transformation, whereas genetic disruption of ptgs-1 greatly reduced cancer incidence both in skin and colon." (PMID 24098505, 2013). "In the current study, we searched the literature to determine the association between PTGS1 or PTGS2 polymorphisms and NSAID use on the risk of developing cancer." (PMID 23967159, 2013). "To date, several studies have investigated associations of the polymorphisms in the PTGS1 and PTGS2 genes and NSAID use on cancer risk; however, these studies have produced mixed results." (PMID 23967159, 2013). "Certain SNPs in PTGS1 and PTGS2 genes have been linked to cancer." (PMID 40184332, 2025). "Therefore, we performed a meta-analysis to evaluate the association between the PTGS1 and PTGS2 polymorphisms and the effect of NSAID use on the risk of developing cancer." (PMID 23967159, 2013). "Our meta-analysis showed that the NSAID users had a lower risk of developing cancer compared with the non-NSAID users among individuals homozygous for the major allele of PTGS1 rs3842787." (PMID 23967159, 2013). "Therefore, we performed a meta-analysis to determine the association between the polymorphisms in PTGS1 and PTGS2 and NSAID use on the risk of developing cancer." (PMID 23967159, 2013). "However, to date, very little is known about ZC2HC1A and PTGS1 and their roles in cancer." (PMID 31215439, 2019). "Although many SNPs located in the region of PTGS1 are known, 1 polymorphism (rs3842787) was analyzed by 3 independent researchers to determine whether the gene polymorphism and NSAID use is associated with cancer risk." (PMID 23967159, 2013). "Furthermore, it is suggested that genetic variation in PTGS1 and PTGS2 might be related to cancer risk and/or drug efficacy in humans." (PMID 23967159, 2013). "In addition, there was the lack of specificity for cancer type in our analysis because few studies have investigated the effect of associations between polymorphisms in PTGS1 and PTGS2 genes and NSAID use on cancer risk." (PMID 23967159, 2013). "Cyclooxygenases play a central role in inflammatory processes, and the link between cancer and inflammation has prompted investigations about PTGS1 and PTGS2 expression across many cancer types." (PMID 40444088, 2025). "AA can produce prostaglandins (PGs) through the action of PTGS1 (COX‐1) and/or PTGS2 (COX‐2), thereby influencing normal development, tissue homeostasis, inflammation, and cancer progression." (PMID 39129202, 2024). "Out of 52 genes investigated, we observed that many genes upregulated in M2 and downregulated in M1 macrophages–ACTN1, FLRT2, MRC1, PTGS1, RHOJ, TMEM158–correlated positively with the EMT scores (first 6 rows) across multiple cancer types." (PMID 30729096, 2019). "We revealed for the first time that in a panel of 96 genes involved in oxidative stress, proliferation, apoptosis and cancer only three genes were changed, GRX2, RNF7, and PTGS1." (PMID 27756324, 2016).
cancer (continued). "IL-27 caused, in both cell lines, a significant down-regulation of a series of anti-angiogenesis related genes namely FGFR3, PTGS1 and, particularly, FLT1, which has been reported to be firmly and strongly expressed in hPCa and involved in cancer cell proliferation via autocrine VEGF signaling." (PMID 24681516, 2014). "For PTGS1 rs3842787, NSAID users homozygous for the major allele (CC) had a significantly decreased cancer risk compared with non-NSAID users (OR = 0.73, 95% CI = 0.59–0.89)." (PMID 23967159, 2013). "For PTGS1 rs3842787, NSAID users homozygous for the major allele (CC) demonstrated a significantly decreased cancer risk compared with non-NSAID users (OR = 0.73, 95% CI = 0.59–0.89)." (PMID 23967159, 2013). "Of the four upregulated (C2HC1A, MARCKSL1, PTGS1, CDKN2B) and five (CLEC10A, PRDX3, PRKCH, MPEG1, LMO2) downregulated genes in poor prognosis patients, several signature genes have direct or indirect roles in cancer immune environment (CLECL10A, PTGS1, C2HC1A)." (PMID 38144522, 2023). "Several studies have investigated whether the polymorphisms in the prostaglandin endoperoxide synthase 1 (PTGS1) and PTGS2 genes and nonsteroidal anti-inflammatory drug (NSAID) use are associated with cancer risk; however, those studies have produced mixed results." (PMID 23967159, 2013).
infection (5 papers, 2016 to 2024). The state of being infected such as from the introduction of a foreign agent such as serum, vaccine, antigenic substance or organism. "Infection with C. difficile suppressed colonic expression of the Ptgs1 and Ptgs2 genes, encoding COX-1 and COX-2, respectively." (PMID 30622186, 2019). "Several genes were significantly upregulated (Pla2g4a, Pla2g4c, Pla2g7, Ptgs1, Ptgs2, Pla1, Tbxas1) or downregulated (Alox5, Pla2g2d, Pla2g1b, Pla2g4b, Pla2g4f) during infection." (PMID 35812400, 2022). "However, the transcript levels of the genes encoding arachidonate 5-lipoxygenase (Alox5), which is involved in leukotriene (LT) biosynthesis, and constitutive Ptgs1 both declined in neutrophils on ST infection." (PMID 27363812, 2016). "However, pharmacological inhibition of PG production, that is, inhibition of Ptgs1 and 2 or specifically Ptgs2, fully reversed the higher infection resistance of larvae forced to express Gbp4 but, unexpectedly, the resistance of larvae forced to express Asc was unaffected." (PMID 27363812, 2016).
brain disorder (1 paper, 2021). A disease affecting the brain or part of the brain. "The predicted affinity of compounds 1a–f at microtubule-associated protein tau, PTGS1/PTGS 2 and their predicted brain disorders applicability." (PMID 34299440, 2021).
gastrointestinal disorders (1 paper, 2021). "Variables: UGIB (outcome), genetic variants in PTGS1 and NOS3 genes (independent), and sex, age, schooling, ethnicity, previous history of gastrointestinal disorders, Helicobacter pylori serology, comorbidity, drug therapy, and lifestyle (confounding)." (PMID 34290607, 2021).
PTGS1 also shares sentences with these, for which no sentence is quoted: cardiovascular disease (7 papers); chronic rhinosinusitis (7); nasal polyps (7); ulcer (6); acute coronary syndrome (4); Allergy (3); metabolic disease (3); angioedema (2); chronic rhinosinusitis with nasal polyps (2); Cirrhosis (2); cognitive deficits (2); colon adenocarcinoma (2); dementia (2); hyperglycaemia (2); insomnia (2); metabolic syndrome (2); myocardial ischemia (2); pancreatic ductal adenocarcinoma (2); papillary thyroid carcinoma (2); rhinitis (2); adenocarcinoma (1); adenoma (1); adhesive capsulitis (1); adult onset asthma (1); allergic rhinitis (1); amyloid (1); aneurysm (1); Anxiety (1); Arterial thrombosis (1); aseptic loosening (1).
A further 71 diseases each share a sentence with PTGS1 in 1 paper.